PDCD1 (programmed cell death 1)
Diseases named in the same sentence as PDCD1 in open-access papers (continued):
Sharing a sentence is not in itself a finding about the gene and the disease.
diabetes (11 papers, 2018 to 2026). "Contrary to previous reports, no distinct immunogenic signature was identified in PDAC with diabetes, as key immune checkpoint genes (Programmed Cell Death Protein 1 (PDCD1), Cytotoxic T-Lymphocyte Associated Protein 4 (CTLA4), Programmed Death-Ligand 1(PD-L1)) were not differentially expressed." (PMID 40244011, 2025). "We profiled the expression of PDCD1 (PD-1) and CTLA4, two immune checkpoint genes previously implicated as defining immunogenic subsets of PDAC-associated diabetes." (PMID 40244011, 2025). "Programmed cell death-1 is expressed on the beta cells of islets of the pancreas, and their destruction can result in hyperglycemia and the onset of new diabetes mellitus (DM)." (PMID 35651416, 2022). "Additionally, PDCD1 did not correlate with time since diabetes diagnosis, INS, or GCG, suggesting a lack of a direct link between islet hormone depletion and PD-1–mediated immune modulation." (PMID 40244011, 2025).
mesothelioma (11 papers, 2019 to 2026). A usually malignant and aggressive neoplasm of the mesothelium which is often associated with exposure to asbestos. "Retrospective studies have shown that high tumor expression of programmed cell death-ligand 1 (PD-L1), known to inhibit T-cell function when bound to the programmed cell death-1 (PD-1) protein, is associated with poor prognosis in patients with mesothelioma." (PMID 39409190, 2024). "Immunotherapies targeting immune checkpoint molecules such as PD-1 (programmed cell death 1), PD-L1 (programmed cell death 1-ligand 1), and CTLA-4 (cytotoxic T-lymphocyte-associated antigen 4) may be effective treatments for mesothelioma." (PMID 40002287, 2025).
nasopharyngeal carcinoma (11 papers, 2021 to 2025). A carcinoma arising from the nasopharyngeal epithelium. "Patients with recurrent or metastatic nasopharyngeal carcinoma (RM-NPC) have proven benefit from anti-programmed cell death 1 (anti-PD-1) monotherapy." (PMID 38961378, 2024). "Are plasma EBV DNA titers associated with outcomes for patients with recurrent or metastatic nasopharyngeal carcinoma (RM-NPC) receiving anti–programmed cell death 1 (anti–PD-1) monotherapy?" (PMID 35230439, 2022). "Anti–programmed cell death 1 (anti–PD-1) immunotherapy features a durable response and improved survival in a small subset of patients with recurrent or metastatic nasopharyngeal carcinoma (RM-NPC)." (PMID 35230439, 2022).
Cirrhosis (10 papers, 2012 to 2025). A chronic disorder of the liver in which liver tissue becomes scarred and is partially replaced by regenerative nodules and fibrotic tissue resulting in loss of liver function. "For PDCD1 rs10204525, where the presence of the variant allele acquired significance after adjusting for age, sex, cirrhosis and T2DM, the odds ratio and significance after conditioning on the fat regulatory genes was enhanced." (PMID 33808740, 2021). "In the conditioned univariate analysis, the protective effect of PDCD1 rs7421861 minor allele remained strikingly significant, after adjusting for age, sex, cirrhosis and T2DM." (PMID 33808740, 2021). "Most notably, up-regulation of caspase-9 and epithelial membrane protein 1 (EMP1) was associated with fibrosis and Bcl-2-related proline-rich protein (BCL2L12) and programmed cell death protein 1 precursor (PDCD1) was associated with cirrhosis." (PMID 27280444, 2016). "We report that the genetic predisposition to HCC development in NAFLD may be influenced by immunoregulatory genes—most notably in this study, PDCD1—in addition to genes predisposing to increased fat accumulation and progression to advanced fibrosis and cirrhosis." (PMID 33808740, 2021). "PNPLA3 and TM6SF2 SNPs were associated with both progression to cirrhosis and NAFLD-HCC development, while PDCD1 SNPs were specifically associated with NAFLD-HCC risk, regardless of cirrhosis." (PMID 33808740, 2021). "Regulation of apoptotic inducer and program cell death genes, BCL212 and PDCD1 in cirrhosis is according to previous observations where pro-apoptotic gene signaling has been observed in infection with HCV." (PMID 22397681, 2012). "In Peng’s study, as compared to patients without HCC (asymptomatic carriers, chronic hepatitis, and cirrhosis), the genotype GA of PDCD-1 rs36084323 was independently associated with HCC in Chinese patients (P = 0.024, OR = 0.459)." (PMID 37131179, 2023). "Moreover, the ACGC haplotype, exhibiting higher PDCD1 mRNA and a lower IFNλ4 protein expression, discriminates cirrhosis from HCC." (PMID 32937024, 2021). "By univariate analysis, the SNPs in PNPLA3, TM6SF2 and PDCD1 rs7421861 were significantly different in NAFLD-HCC versus controls, but none retained significance after regression analysis including age, sex and cirrhosis." (PMID 33808740, 2021). "In this study, host genes involved in apoptosis such as BCL212 and PDCD1 showed down-regulation in initial fibrosis and significant up-regulation in cirrhosis, whereas, expression levels for CASP9 and EMP1 genes were high at initial stage and were down-regulated in cirrhosis stage." (PMID 22397681, 2012). "In addition, linkage disequilibrium analysis (LD) evidenced a linkage that did not occur by chance (LD >50) between PDCD1 SNPs and rs12979860 of IFNL4 in BD and in patients with CHC, MC and B‐NHL but not in patients with cirrhosis or HCC." (PMID 32937024, 2021).
colitis (10 papers, 2017 to 2025). Inflammation of the colon. "Pdcd1-deficient mice develop colitis, and FAO inhibition effectively restores IL-22 production in Pdcd1-deficient T cells, reducing inflammatory responses." (PMID 40155378, 2025). "Ctla4 was the most highly upregulated checkpoint gene in all the colitis models, with less pronounced changes in the expression of Pdcd1, Lag3, Vsir and Havcr2." (PMID 39496592, 2024). "Checkpoint-inhibitors like nivolomab and pembrolizumab, targeting programmed cell death-1 (PD-1), or ipilimumab, blocking CTLA-4, can induce adverse autoimmune reactions like hepatitis, colitis, rash, endocrinopathies and pneumonitis." (PMID 28895915, 2017).
pneumonitis (10 papers, 2020 to 2025). An inflammatory process affecting the lung parenchyma. "Incidentally, the patient was diagnosed two years ago with hypothyroidism, hypophysitis, secondary adrenal insufficiency, and pneumonitis, each suspected to be secondary to treatment with pembrolizumab (Keytruda), a monoclonal anti-programmed cell death-1 antibody." (PMID 32724737, 2020). "The potential similarities with anti-programmed cell death 1 inhibitor-related pneumonitis have not been studied to our knowledge." (PMID 38605470, 2025). "However, an anti-programmed cell death 1 (aPD-1) antibody alone in normal mice is not sufficient to induce pneumonitis." (PMID 39762211, 2025).
acute myeloid leukemia (9 papers, 2020 to 2025). Acute myeloid leukemia (AML) is a group of neoplasms arising from precursor cells committed to the myeloid cell-line differentiation. "The potential association between the PDCD1 rs2227981 and LAG3 rs12313899 polymorphisms and risk of acute myeloid leukemia (AML) was studied through stratified analyses based on gender and age." (PMID 38792904, 2024). "This study aimed to investigate the correlation between SNPs of two inhibitory immune checkpoint receptors PDCD1 rs2227981 and LAG3 rs12313899 and the susceptibility to acute myeloid leukemia in the Saudi population." (PMID 38792904, 2024).
atherosclerosis (9 papers, 2014 to 2026). A disease characterized by the build-up of fatty material and calcium deposition in the arterial wall resulting in partial or complete occlusion of the arterial lumen. "In mice with advanced atherosclerosis, Foxp3, Ifng, Il21, and Pdcd1 mRNA levels were increased in the splenic CD3+ cells indicating that atheroprogression drives T-cell activation and regulatory transcriptional programs." (PMID 38270847, 2024). "Moreover, in the age-matched mice with more advanced atherosclerosis due to severe dyslipidemia, miR-15a-5p correlated positively with Pdcd1 and Ifng mRNA and inversely with plasma cholesterol and triglyceride levels." (PMID 38270847, 2024). "Additionally, CD69 promotes programmed cell death 1 (PD-1) expression in CD4+ T lymphocytes after engagement with oxLDL, which may be responsible for the exacerbated activation state found in the absence of CD69 in an atherosclerosis model." (PMID 39817455, 2025).
Merkel cell carcinoma (9 papers, 2017 to 2025). "ctDNA measurement was used to track the disease course in two patients with Merkel cell carcinoma whose disease had progressed on pembrolizumab, a programmed cell death-1 (PD-1) inhibitor." (PMID 37685358, 2023).
squamous cell carcinoma (9 papers, 2018 to 2025). A carcinoma arising from squamous epithelial cells. "Concordantly, we observed higher expression of immune checkpoint proteins (CTLA4, TIGIT, and PDCD1) in the lymphocytes at the invasive front of squamous cell carcinomas." (PMID 41309580, 2025).
T-cell lymphomas (9 papers, 2020 to 2025). "Accordingly, loss of PDCD1 leads to increased PI3K-AKT signaling that contributes to T cell lymphoma development." (PMID 32811551, 2020). "The PD-1 gene (PDCD1) has been shown to be a haploinsufficient tumor suppressor that is frequently altered in T-cell lymphomas, and it is mutationally truncated, as well as heterozygously and biallelically deleted, in advanced MF and in SS patients (10–40% of cases)." (PMID 33923722, 2021). "Actually, mono- and bi-allelic deletion of PDCD1, the gene coding for PD-1, have been detected in more than 30% of T-cell lymphomas and rapid disease progression has been documented in some patients treated with anti-PD-1 mAbs for T-cell malignancies." (PMID 33072126, 2020).
clear cell renal cell carcinoma (8 papers, 2019 to 2026). "We hypothesized that single nucleotide polymorphisms (SNPs) in the PDCD1 and CD274 genes, encoding PD-1 and PD-L1, are associated with clinicopathological features, PD-L1 immunohistochemical expression, and clinical outcomes in clear cell renal cell carcinoma (ccRCC)." (PMID 42074079, 2026). "In renal clear cell carcinoma, TRPV3 can induce the expression of immune checkpoints such as LAG3, CTLA4, PDCD1, and TIGIT, leading to the accumulation of immunosuppressive T cells in the tumor microenvironment." (PMID 41331166, 2025).
hypophysitis (8 papers, 2020 to 2025). Inflammation of the pituitary gland. "Most underlying mechanisms of ICI-related hypophysitis remain unclear, especially for programmed cell death-1 (PD-1)/PD-1 ligand 1 (PD-L1) inhibitors." (PMID 33977343, 2021). "Immune checkpoint inhibitors induce hypophysitis (IIHs): IIHs is an increasingly frequent toxicity of in patients on treatment with inhibitors targeting cytotoxic T-lymphocyte antigen 4 (CTLA-4) and programmed cell death-1 (PD-1)." (PMID 37623461, 2023). "Hypophysitis is an increasingly frequent endocrine toxicity of clinical significance observed in patients on treatment with ICIs, particularly monoclonal antibodies (mAbs) that target cytotoxic T-lymphocyte antigen 4 (CTLA4) and programmed cell death-1 (PDCD1)." (PMID 41465179, 2025). "Hypophysitis is an increasingly frequent endocrine toxicity of clinical significance observed in patients on treatment with ICIs, particularly monoclonal antibodies (mAbs) that target cytotoxic T-lymphocyte antigen 4 (CTLA-4) and programmed cell death-1 (PD-1)." (PMID 37623461, 2023).
leukemia (8 papers, 2017 to 2025). A malignant (clonal) hematologic disorder, involving hematopoietic stem cells and characterized by the presence of primitive or atypical myeloid or lymphoid cells in the bone marrow and the blood. "The PDCD1 rs2227981 G allele, situated in exon 5 of the PD-1 gene, was found to be more prevalent in AML patients than in healthy controls, indicating its possible involvement in regulating immune evasion mechanisms in leukemia." (PMID 38792904, 2024).
psoriasis (8 papers, 2019 to 2025). An autoimmune condition characterized by red, well-delineated plaques with silvery scales that are usually on the extensor surfaces and scalp. "Their research aimed to determine the association between these genetic polymorphisms in PDCD1 and the pathophysiology of psoriasis." (PMID 40343299, 2025). "Consistently, mice with Pdcd1 deletion on CD8+ T cells are more susceptible to psoriasis-like dermatitis induced by imiquimod (R848, a toll-like receptor 7/8 agonist), which is ameliorated by anti-IL-6 receptor blockade." (PMID 35154081, 2021). "A study utilized spatial transcriptomics to compare the expression of inhibitory T cell ICs, specifically CTLA-4, TIGIT, LAG-3, and PDCD1 (encoding PD-1), on tissue-resident memory T cells in patients with dermatomyositis (Th1-driven) and psoriasis (Th17-driven)." (PMID 38817600, 2024). "In psoriasis, DN T cells are characterized by increased surface expression of the programmed cell death 1 (PD1) co-receptor, a regulatory “immune checkpoint” that is involved in the termination of inflammatory responses and immune homeostasis." (PMID 31333659, 2019).
skin cancer (8 papers, 2018 to 2025). "These analyses also provided us with a unique opportunity to test the impact of immunotherapy with anti-programmed cell death-1 (PD-1) in skin cancer-infiltrating MAIT cells." (PMID 32849590, 2020). "Additionally, we observed high expression of Pdcd1 in skin tumors, highlighting the potential role of CD4+ T cells in checkpoint inhibitor immunotherapy." (PMID 40282557, 2025). "In addition, this T-cell cluster exhibited over-expression of exhaustion marker genes such as Tox, Pdcd1, Tigit, Havcr2, Lag3, and Ctla4 in the T cell cluster in skin tumors, suggesting the emergence of T-cell exhaustion in skin tumors." (PMID 40282557, 2025).
hepatitis B (7 papers, 2019 to 2025). "In addition, previous studies have indicated associations of PDCD1 rs2227982 with host susceptibility to hepatitis B infection and risk of Mycobacterium avium complex lung disease in women." (PMID 38723011, 2024). "Low levels of intracellular free Mg2+ also lead to increased expression of the immune checkpoint programmed cell death 1 (PD-1) along with lower expression of NKG2D in hepatitis B-infected NK and CD8+ T cells." (PMID 35558754, 2022).
liver disease (7 papers, 2019 to 2025). "The expression of the Pdcd1 gene (encoding PD-1) was increased alongside the progression of the liver disease, from inflammation to the development of the tumor (ANOVA p < 0.05)." (PMID 37686163, 2023). "Further examination revealed associations between PDCD1 SNP genotypes and type of liver disease." (PMID 32937024, 2021). "Immune dysregulation is widely reported in patients with advanced liver disease, and our gene expression data showed significant differences in IL-10 and PDCD1 gene expression between patients with AD and healthy volunteers." (PMID 40126412, 2025). "We investigated the IFNL4 rs12979860 and the PDCD1 polymorphisms in 734 HCV‐positive patients, including 461 cases with liver disease of varying severity and 273 patients with lymphoproliferative disorders to determine the association of these genes with patient's outcome." (PMID 32937024, 2021).
Arthritis (6 papers, 2017 to 2024). Inflammation of a joint. "I read with interest the case report entitled “Arthritis and myositis in a patient with programmed cell death-1 (PD-1) inhibitor pembrolizumab for lung cancer”, recently published in the Mediterranean Journal of Rheumatology." (PMID 34447920, 2021).
B-cell lymphoma (6 papers, 2020 to 2023). "Camrelizumab is a programmed cell death 1 (PD-1) inhibitor that was recently investigated as a treatment for various malignancies, including B cell lymphoma, Hodgkin lymphoma, HCC, gastric and gastroesophageal cancers, and nonsmall cell lung cancer." (PMID 35207638, 2022). "Clinical studies have also demonstrated that programmed cell death-1 (PD-1) inhibitors, such as pembrolizumab, are effective in B-cell lymphoma, but their value in primary lymphoma of the prostate remains to be further investigated." (PMID 34727993, 2021).
Hepatitis (6 papers, 2021 to 2024). Inflammation of the liver. "The incidence of ICI-derived hepatitis is approximately 1-3% for programmed cell death 1 (PD1) inhibitors and 3-9% in cytotoxic T-lymphocyte-associated protein 4 (CTLA4) inhibitors." (PMID 37205101, 2023).
pancreatic ductal adenocarcinoma (6 papers, 2016 to 2025). An infiltrating adenocarcinoma that arises from the epithelial cells of the pancreas. "For instance, the combination of programmed cell death 1 (PD-1) inhibitors with chemotherapy drugs has shown both efficacy and safety in treating metastatic pancreatic ductal adenocarcinoma with liver metastases, offering new insights for LIHC treatment." (PMID 41194934, 2025). "We examined the prognostic value of programmed cell death-1 (PD-1) and its ligand (PD-L1) together with CD8+ tumor-infiltrating lymphocytes (TILs) and FOXP3+ Tregs in resectable pancreatic ductal adenocarcinoma (PDAC) samples treated with adjuvant chemotherapy." (PMID 27329602, 2016).
asthma (5 papers, 2021 to 2025). "The Treg and Th17 cell balance can be affected by passive smoke inhalation, adenosine receptor A2AR, and the programmed cell death-1 (PD-1)/PD-ligand 1 (PD-L1) pathway; all of which can contribute to the severity of asthma in children." (PMID 34239942, 2021). "Cd274 and Pdcd1 were reported to be important for the activation of T lymphocytes in asthma and PD-1 expression increased in T-CD4+ lymphocytes of asthmatic patients." (PMID 34440118, 2021). "Although not a prominent gene to come out of this analysis, PDCD1 has been shown in a small study to be increased in asthma patients after whole lung allergen challenge." (PMID 35386986, 2021).
basal cell carcinoma (5 papers, 2020 to 2025). A carcinoma involving the basal cells. "According to our best knowledge, there are only individual articles regarding PDCD1 polymorphisms in relation to thyroid cancer, head and neck squamous cell carcinomas, brain tumor, cutaneous melanoma and basal cell carcinoma." (PMID 33519815, 2020). "Other treatment options include the use of imiquimod 5% cream for basal cell carcinomas, the SMO (smoothened) inhibitor vismodegib, the PD-1 (programmed cell death-1) inhibitor pembrolizumab and systemic retinoids." (PMID 34440347, 2021).
dilated cardiomyopathy (5 papers, 2018 to 2023). Cardiomyopathy which is characterized by dilation and contractile dysfunction of the left and right ventricles. "In 2001, it was discovered that BALB/c mice with the PDCD1−/− genotype develop dilated cardiomyopathy." (PMID 36672615, 2023). "BALB/c mice with Pdcd1 ablation develop dilated cardiomyopathy with the deposition of IgG antibodies on the surface of cardiomyocytes." (PMID 36979163, 2023). "For instance, germline deletion of Pdcd1 in BALB/c mice results in dilated cardiomyopathy, while C57BL/6 mice with Pdcd1 knockout present no cardiac phenotype." (PMID 35844550, 2022).
endometriosis (5 papers, 2021 to 2025). The growth of functional endometrial tissue in anatomic sites outside the uterine body. "We found that PDCD1 was significantly higher in the endometrium, while PDCD1LG2 was substantially higher in endometriosis." (PMID 40165344, 2025). "In addition, we explored the immune checkpoints (PDCD1, PDCD1LG2, CTLA4, TNFRSF9, and TNFRSF4) expression levels between the endometrium and endometriosis." (PMID 40165344, 2025). "We also identified putative inhibitory interactions between endometriosis immune cells and ectopic FBs rather than eutopic FBs, including KLRB1, TIGIT, and PDCD1, which were highly expressed by NK and T cells, and potentially bind to CLEC2D, NECTIN3, and FAM3C, which were expressed by FBs." (PMID 34233737, 2021).